CEACAM4 (CEA cell adhesion molecule 4)
Description:
Granulocyte orphan receptor that acts as an trigger efficient phagocytosis of attached particles.
Synonyms: CGM7; CGM7_HUMAN; NCA
Tractability: Antibody: its Gene Ontology location is reachable by antibodies, with high confidence; UniProt predicts a signal peptide or a membrane-spanning region.
Gene: Protein-coding gene on chromosome 19 (41,619,015 to 41,627,074, reverse strand). Ensembl gene ENSG00000105352.
Subcellular location: Membrane
Gene Ontology:
Molecular function: protein binding; protein tyrosine kinase binding
Biological process: phagocytosis; regulation of immune system process; signal transduction
Cellular component: cell surface; membrane; plasma membrane
Genetic constraint (gnomAD): Loss-of-function variants: 27 observed, 25.64 expected, observed/expected ratio (o/e) 1.05, 90% interval 0.77 to 1.45. The upper end of that interval is the gene's LOEUF score, 1.45, which puts it in group 6 of 6, group 1 being the genes least tolerant of losing a copy. Missense variants: 309 observed, 286.51 expected, observed/expected ratio (o/e) 1.08, 90% interval 0.98 to 1.18. Synonymous variants: 137 observed, 120.5 expected, observed/expected ratio (o/e) 1.14, 90% interval 0.99 to 1.31.
Homologues: Orthologues: chimpanzee CEACAM4 (91% identical), macaque CEACAM4 (78% identical). Paralogues in human: CEACAM3 (54% identical), CEACAM1 (45% identical), CEACAM21 (45% identical), CEACAM6 (36% identical), CEACAM8 (36% identical), CEACAM5 (35% identical), CEACAM7 (32% identical), PSG2 (31% identical), PSG6 (31% identical), PSG11 (30% identical), PSG5 (30% identical), PSG8 (30% identical), and 12 more.
Diseases named in the same sentence as CEACAM4 in open-access papers:
CEACAM4 is named in the same sentence as 12 diseases in open-access papers, as found by Europe PMC text mining. Sharing a sentence is not in itself a finding about the gene and the disease. The quoted sentences say what the papers report.
Sepsis (4 papers, 2015 to 2024). Sepsis is defined as life-threatening organ dysfunction caused by a dysregulated host response to infection. "Reduced levels of CEACAM4, encoding a phagocytosis-mediating receptor, in whole blood of sepsis patients are integral to the SeptiCyteTM LAB test." (PMID 39434093, 2024). "Only the cell membrane protein encoding genes CXCR2 and CEACAM4 were more highly expressed in SIRS than sepsis." (PMID 39434093, 2024). "Particularly, HD granulocytes showed higher levels of the PMN-expressed Cell Membrane pathway genes CXCR2 and CEACAM4 in SIRS than sepsis." (PMID 39434093, 2024). "But using the levels of CEACAM4 in the HD fraction as a reference for PLAC8, also a SeptiCyteTM LAB gene, and CD63 in the LD fraction still improved the sepsis-SIRS distinction by these two azurophilic granule genes compared to their unreferenced LD levels." (PMID 39434093, 2024). "The granule biogenesis pathway genes CEACAM4, PLAC8, and CD63 were analyzed by quantitative real-time polymerase chain reaction (qRT-PCR) and their abilities to distinguish sepsis and SIRS were compared to the routine infection marker CRP (C-reactive protein)." (PMID 39434093, 2024). "For instance, the first host response gene expression assay for diagnosis of sepsis, SeptiCyte LAB, is based on the four marker genes CEACAM4, LAMP1, PLAC8 and PLA2G7." (PMID 34555028, 2021). "Recently, many genes have also been identified for sepsis diagnosis and prognosis; for example, SeptiCyte Lab combined with CEACAM4, LAMP1, PLA2G7, and PLAC8 genes was identified to determine which patients had sepsis." (PMID 32922168, 2020). "Taken together, this indicates that elevated expression of CD63 but not PLAC8 in sepsis is restricted to LD granulocytes and that a concomitant reduction of CEACAM4 expression in HD granulocytes improves the ratiometric discrimination between sepsis and SIRS." (PMID 39434093, 2024). "CEACAM4, however, appeared not only more highly expressed in total and HD granulocytes than in the LD fraction of septic shock patients, consistent with PMNs as their source, but also showed higher levels in SIRS than sepsis HD granulocytes." (PMID 39434093, 2024). "Given the absence of any differences between sepsis and SIRS in PMN blood counts and their proportions in both HD and LD granulocytes, PMNs appear to express lower levels of CXCR2 and CEACAM4 in sepsis than SIRS." (PMID 39434093, 2024).
COVID-19 (2 papers, 2021 to 2024). A disease caused by infection with severe acute respiratory syndrome coronavirus 2. "In this study, we identified 156 shared genes between the COVID-19 and KIRC cohorts and selected four hub genes (GTSE1, CEACAM4, HECW2, and KCNMA1) as the foundation for developing a risk model." (PMID 38464749, 2024). "To identify potential drugs for the treatment of COVID-19 and KIRC co-morbidity, we conducted drug target enrichment analysis with four hub genes (GTSE1, CEACAM4, HECW2, and KCNMA1) as genetic targets associated with the construction of risk models via cellMiner and DsigDB databases." (PMID 38464749, 2024).
breast carcinoma (1 paper, 2021). "Two stop gain mutations in CEACAM4 were associated with African American breast cancer, and two splicing mutations were associated with European American breast cancer, one in CEACAM6 and another within CEACAM8." (PMID 34447411, 2021). "However, gene-based aggregation analyses did not support CEACAM4 as a breast cancer risk gene." (PMID 34447411, 2021). "Interestingly, in a study of parous women with and without breast cancer, CEACAM4 has been reported to be up-regulated in normal breast compared to breast tumor samples." (PMID 34447411, 2021). "Though race/ethnicity was not revealed in that study, the results suggest that CEACAM4 could be a breast cancer tumor suppressor." (PMID 34447411, 2021).
Shock (1 paper, 2024). The state in which profound and widespread reduction of effective tissue perfusion leads first to reversible, and then if prolonged, to irreversible cellular injury. "Because promyelocytes express PLAC8 and PMNs CEACAM4, and potentially sustain high levels of PLAC8, the expression of these genes may be expected to not increase further with disease severity, as in septic shock, as a result of elevated precursor counts." (PMID 39434093, 2024).
tumor (5 papers, 2020 to 2025). "CEACAM4, a constituent of the carcinoembryonic antigen family, is frequently overexpressed in cancer and often signifies tumor invasion." (PMID 38464749, 2024). "Spearman correlations analysis showed that CRYBB1, CEACAM4, HAMP, and LYL1 were highly positively associated with tumor‐infiltrating lymphocytes in ccRCC." (PMID 34402193, 2021). "Phenotype association analysis suggested all of hub genes involved in tumor development, and it seems CRYBB1, CEACAM4, and HAMP correlated with ccRCC progression more than another two (RIMBP3C and LYL1)." (PMID 34402193, 2021). "All of these indicated CEACAM4 was highly related to both immune and tumor." (PMID 34402193, 2021). "Additionally, genes involved in extracellular matrix remodelling and adhesion, such as PLAUR, PLG and CEACAM4, may enhance tumour invasion by modifying the tumour microenvironment, a process extensively reported in invasive malignancies." (PMID 40830065, 2025). "Tumor microenvironment analysis in TISIDB and GSE73731 confirmed that CRYBB1, CEACAM4, HAMP, and LYL1 were highly related to tumor‐infiltrating lymphocytes." (PMID 34402193, 2021). "Spearman correlations analysis indicated that CRYBB1, CEACAM4, HAMP, and LYL1 were positively related to different kinds of tumor‐infiltrating lymphocytes across many tumor types while RIMBP3C showed consistently statistical insignificance." (PMID 34402193, 2021). "CEACAM4 is a member of carcinoembryonic antigen‐related cell adhesion molecule (CEACAM) family, which is expressed highly in tumors and secreted in serum, and has been widely used as human tumor markers." (PMID 34402193, 2021). "Also, Tregs from NI ad I TDLN share CD58, ITGAM, MCAM, CEACAM4, SELPLG, and HMMR expression, which could ensure recirculation among TDNLs; and Tregs from I TDLN and tumor Tregs share ICAM1 expression, which could be responsible for the migration among tissues with presence of tumor cells." (PMID 32601304, 2020).
cancer (2 papers, 2021 to 2024). A tumor composed of atypical neoplastic, often pleomorphic cells that invade other tissues. "In addition, CEACAM4 was enriched in VEGF signaling pathway (p‐value: 0.027) and MAPK signaling pathway (p‐value: 0.040) and HAMP was significantly associated with pathways in cancer (p‐value: 3.24e−04) and MAPK signaling pathway (p‐value: 6.98e−03)." (PMID 34402193, 2021).
CEACAM4 also shares sentences with these, for which no sentence is quoted: breast tumor (1 paper); infection (1); medullary thyroid carcinoma (1); melanoma (1); Sciatica (1); septic shock (1).